ENSG00000275778 (PRH1-PRR4 readthrough)
Synonyms: PRH1-PRR4
Gene: Protein-coding gene on chromosome 12 (10,845,849 to 11,171,598, reverse strand). Ensembl gene ENSG00000275778.
Genetic constraint (gnomAD): Loss-of-function variants: 5 observed, 4.02 expected, observed/expected ratio (o/e) 1.24, 90% interval 0.62 to 1.9. That is too few expected variants to judge how well the gene tolerates losing a copy. Missense variants: 124 observed, 114.77 expected, observed/expected ratio (o/e) 1.08, 90% interval 0.93 to 1.25. Synonymous variants: 36 observed, 38.32 expected, observed/expected ratio (o/e) 0.94, 90% interval 0.72 to 1.24.